TNF (tumor necrosis factor)
Diseases named in the same sentence as TNF in open-access papers (continued):
Sharing a sentence is not in itself a finding about the gene and the disease.
malnutrition (continued). "Increased levels of duodenal IL-17A, IL-21, IL-22, CXCL5 due to malnutrition—together with decreased levels of TNFα, IL-12, TGFβ and CXCL10 and elevated levels of IgA due to infection—revealed that the duodenum was sensitive to both variables and suggested local inflammation in malnourished animals." (PMID 34207946, 2021). "Meanwhile, several proinflammatory cytokines, such as TNF alpha, IL 6, and hormones would be produced by the tumor directly or systemically in response to the tumor, which had also been reported in the pathogenesis of malnutrition." (PMID 34708064, 2021). "Elevated levels of IL-6 and TNFα may primarily be related to infections, and support the observation that induction of an acute phase response is intact in malnutrition." (PMID 25153531, 2014). "Malnutrition in dialysis patients has been linked to elevated levels of tumor necrosis factor-α (TNF-α), therefore, malnutrition risk could potentially contribute to the development of small fiber neuropathy in this patient population by exacerbating inflammatory and oxidative stress pathways." (PMID 41289277, 2025). "Moreover, malnutrition has been shown to exacerbate chronic inflammatory responses in diabetic patients through its influence on inflammatory mediator expression, including tumor necrosis factor-alpha (TNF-α) and interleukin-6 (IL-6)." (PMID 40977986, 2025). "Low BMI, BMC and BFMI were identified as risk factors for the presence of malnutrition (BMI, p = 0.019; BCMI, p = 0.035; BMC, p = 0.014; BFMI, p = 0.007; extracellular water, p = 0.026), suggesting that they would predict the long-term nutritional status of CD patients treated with anti-TNF therapy." (PMID 36824176, 2023). "This study mainly aimed to observe the effect of anti-TNF therapy on the nutritional status of CD patients, to investigate the correlation between the timing of anti-TNF therapy and the human body composition and to examine independent body composition factors for predicting malnutrition." (PMID 36824176, 2023). "However, few studies have reported the benefit of early anti-TNF therapy in relieving malnutrition." (PMID 36824176, 2023). "In this single-center cohort study, authors aimed to investigate which of the chosen inflammatory markers (leptin, IL-18, IL-6, IL-1α, TNFα) may contribute to malnutrition and its consequences the most, and further reflected upon possible interventions, based on the most up-to-date literature." (PMID 36558477, 2022). "Malnutrition promotes the phenotypic transformation of immune cells to pro-inflammatory phenotypes, secreting pro-inflammatory cytokines such as IL-1β, IL-6, IL-8, TNF-α, and IL-2, while anti-inflammatory cytokines such as IL-1 receptor antagonists, IL-4, IL-10, and IL-13 decrease." (PMID 35003070, 2021). "One study, directly comparing spontaneous TNF production in seven patients with anorexia nervosa and six patients with primary malnutrition (infection free), found significantly greater levels in anorexia nervosa when compared to primary malnutrition (p < 0.0006)." (PMID 31717370, 2019). "Mechanistically, the bidirectional relationship between inflammation and malnutrition in IBD is mediated by proinflammatory cytokines (e.g., TNF, IL-6, IL-17), gut microbiota dysbiosis, and protein depletion." (PMID 41538674, 2026). "For example, elevated pro‐inflammatory biomarkers such as tumor necrosis factor‐alpha (TNF‐α), interleukin‐6 (IL‐6), and C‐reactive protein (CRP) are commonly seen in cases of malnutrition." (PMID 39817025, 2025). "As for frailty definition, we adopted Fried’s frailty phenotype (FP), while malnutrition–inflammation syndrome was assessed using the Malnutrition–Inflammation Score (MIS) and circulating inflammatory cytokines (IL-6; TNFα; MCP-1)." (PMID 39203763, 2024).
malnutrition (continued). "Firstly, a higher level of inflammation indicated high levels of cytokines such as IL-1, and IL-6, tumor necrosis factor-alpha and CRP, which greatly accelerates the consumption of nutrition, leading to malnutrition and the progression of CRC." (PMID 37063910, 2023). "This study also verified that the MIS has a good correlation with the malnutrition indicators hemoglobin and prealbumin and inflammation indicators CRP, IL-6, TNF-a and ferritin in PD patients." (PMID 33413177, 2021). "Considering that PTX3 is expressed in different tissues, including in the adipose tissue, this inflammatory biomarker seems to be more sensitive to inflammation-related malnutrition than CRP, IL-6, and TNF-α in this population." (PMID 31316299, 2019). "We therefore derived a nutrient–inflammation interaction score (NIIS) by multiplying log-transformed TNF-α with an inverse-normalised GNRI, reasoning that this composite metric would more faithfully reflect the biological axis along which HF, malnutrition, and carcinogenesis converge." (PMID 41473193, 2025). "The nutritional status of the host also impacts on the levels of cytokines: we have previously shown that malnutrition results in altered cytokine profiles, with negative correlations between BMI and cytokines such as TNF-α and IFN-γ." (PMID 39415297, 2024). "Meanwhile, malnutrition was secondary to IBD, and this chronic inflammation could trigger tumor necrosis factor (TNF) and chemokines to result in protein-energy malnutrition." (PMID 38183088, 2024). "Among all malnutrition patients, 4 (5.63%) patients received anti-TNF therapy, while 18 (40.91%) did not." (PMID 36824176, 2023). "Due to malabsorption and malnutrition, Cluster of differentiation 14 (CD14) levels are elevated in cachectic HF patients in line with increased levels of tumor necrosis factor alpha (TNF-α), indicating an endotoxin release with a concomitant inflammatory response." (PMID 34899373, 2021). "While we see epithelial cell ablation, and dextran leakage from the gut with moderate malnutrition, we do not think there is bacterial translocation in this model, based on lower systemic IFNγ and TNFα observed in the sera." (PMID 33799736, 2021). "Increased transcription of TNF-α in RBD-challenged mice is probably correlated with the increased number of Kupffer cells, as more IBA-1-positive liver cells were found, suggesting an activated inflammatory state in prolonged malnutrition." (PMID 32401929, 2020). "Inflammatory cytokines such as TNF-α and IL-6 inhibit albumin synthesis, indicating that hypoalbuminemia in PD patients may be more attributable to systemic inflammation rather than malnutrition." (PMID 39281816, 2024). "Additionally, in accordance with our Cox proportional hazards model, patients without anti-TNF therapy tended to have a higher probability of malnutrition." (PMID 36824176, 2023). "Inflammatory cytokines, such as TNF, IL-6, and IFN-γ may downregulate lipolytic enzyme activity; however, the pathophysiological activities in IBD are more complex because of the chronic inflammation, malnutrition, and lipid malabsorption due to intestinal damage or resection." (PMID 35770006, 2022).
peritonitis (154 papers, 2005 to 2026). Inflammation of the peritoneum (tissue that lines the abdominal wall and covers most of the organs in the abdomen). "Previous research has demonstrated that increased TMAO induces the production of IL-6 and TNF-α, exacerbating peritoneal inflammation in peritoneal dialysis patients and increasing the risk of peritonitis." (PMID 38500584, 2024). "A study of 748 dialysis patients implicated that PTH < 150 pg/mL was associated with elevated inflammatory markers, including tumor necrosis factor α and C-reactive protein, which were traditional evaluated parameters for peritonitis." (PMID 33514340, 2021). "Infection with ΔbgsA resulted also in significantly increased TNF-α concentrations in the peritoneal lavage fluid 3 h after infection compared to mice with peritonitis caused by wild-type bacteria or ΔbgsB." (PMID 26172831, 2015). "The γδ T cell-driven perpetuation of inflammatory responses during acute peritonitis is associated with elevated peritoneal levels of γδ T cells and TNF-α and detrimental clinical outcomes in infections caused by HMB-PP positive microorganisms." (PMID 21589907, 2011). "Interestingly, if the peritonitis caused by the resistant strains of P. aeruginosa, Epinecidin-1 treatment significantly increased plasma concentrations of IL-1β and TNF-α." (PMID 31138331, 2019). "Postoperative tumor necrosis factor levels were significantly lower in the PPL group compared with the LAP group under mild peritonitis (202 pg/ml vs. 443 pg/ml, p = 0.034)." (PMID 42266150, 2026). "In vivo, the extract reduced glucose and cholesterol levels, inhibited leukocyte and neutrophil infiltration, and suppressed TNF-α and nitric oxide production in the peritonitis model." (PMID 41302395, 2025). "Our results revealed that baicalin can decrease the protein expressions of TNF-α, IL-1β, and IL-6 in GPS-infected PPMCs and piglets, which suggests that the regulation of inflammatory injury is helpful in alleviating peritonitis caused by GPS." (PMID 40867785, 2025). "In a mouse model of LPS-induced peritonitis, treatment with Rhy significantly reduced serum levels of IL-6, TNF-α, and NO." (PMID 41031160, 2025). "Oral administration of LPE has been shown to attenuate peritonitis by reducing pro-inflammatory mediators (IL-1β, IL-6, and TNF-α) and increasing IL-10 secretion." (PMID 40079578, 2025). "We used the PE-labeled CD64 antibody to monitor CD64 expression changes on neutrophils upon TNFα induced peritonitis, demonstrating the feasibility of labeling immune cells using antibodies and monitoring them using IVFC." (PMID 39199274, 2024). "To the best of our knowledge, we are the first to report the noninvasive monitoring of circulating neutrophils and to show neutrophil dynamic changes in the TNFα-induced peritonitis mouse model." (PMID 39199274, 2024). "In the animals with LPS-induced peritonitis, there was a 71.1% increase (p < 0.001) in the levels of the pro-inflammatory cytokine TNF-α compared to the naive group." (PMID 39452085, 2024). "Acting mainly as an anti-inflammatory agent, CecA was able to improve survival after Escherichia coli-induced peritonitis in mice, decreasing the endotoxin and tumor necrosis factor α (TNFα) concentrations in the blood." (PMID 38496311, 2024). "Throughout the development of peritonitis, macrophages produce cytokines such as tumor necrosis factor (TNF)-α and interleukin-6 (IL-6), mediating and promoting pro-inflammatory responses." (PMID 38675622, 2024). "The oral treatment of acute peritonitis with HEVe reduced the total leukocytes, neutrophils, TNF-α, and IL-1β and elevated IL-10 levels." (PMID 39452085, 2024). "Conventional flow cytometry was also used to assess the CD64 expression on blood neutrophils in TNFα-induced peritonitis." (PMID 39199274, 2024). "Here, we blocked CD18 using antibodies and used IVFC to monitor the dynamic changes in circulating neutrophils in TNFα-induced peritonitis." (PMID 39199274, 2024).
peritonitis (continued). "We then monitored neutrophil CD64 expression in vivo and found a significant increase in TNFα-induced peritonitis." (PMID 39199274, 2024). "As expected, CLP-induced peritonitis was associated with strong systemic and local upregulation of pro-inflammatory cytokines IL-6, CCL2, and TNF as well as upregulation of anti-inflammatory IL-10 compared to sham animals." (PMID 38562925, 2024). "A single dose of alginate did not significantly alter the levels of the pro-inflammatory cytokine TNF-α in the peritoneal fluid of rats with a model of peritonitis." (PMID 37103384, 2023). "Flow cytometry analysis of peritoneal cells and measurement of IL-6, IL-1β, and TNF-α levels in the peritoneal lavages confirmed zymosan-induced peritonitis." (PMID 36769096, 2023). "The levels of TNF-α in a model of acute carrageenan-induced peritonitis in rats were also investigated." (PMID 37103384, 2023). "The gene transcription of CAR, IL-1b, and TNF-a was significantly increased in the PMCs of peritonitis mice compared to wild-type mice." (PMID 36982385, 2023). "The serum levels of TNF-α, IL-1β, IL-6, and IL-10 in rats with systemic inflammation, and the levels of TNF-α in a model of acute peritonitis in rats were also investigated." (PMID 37103384, 2023). "Pro-inflammatory cytokines were elevated after 24 h of peritonitis formation, especially IL-1Ra, IL-1b, IL-6, IL-8, and TNF-α." (PMID 38087374, 2023). "Inhibition of SUMOylation with TAK981 can enhance TNFα responses to fight bacterial infection in mild polymicrobial peritonitis." (PMID 37520526, 2023). "A single dose of alginate isolated from C. crinita did not significantly change levels of the pro-inflammatory cytokine TNF-α in the peritoneal fluid of rats with a model of peritonitis in comparison with controls." (PMID 37103384, 2023). "During an acute inflammatory process such as peritonitis, natural killer (NK) cells produce inflammatory cytokines such as tumor necrosis factor alpha (TNF-α) and interleukin (IL-6)." (PMID 35329948, 2022). "Bauhinia bauhinioides (Fabaceae) seed lectin (BBL) reduced carrageenan-induced paw edema and inhibited leukocyte migration and tumor necrosis factor (TNF-α) release in an experimental model of peritonitis in Wistar rats." (PMID 35458359, 2022). "Our findings demonstrating that IFNAR–/– mice have decreased T cell recruitment in TNF-α–induced peritonitis further support this mechanism." (PMID 34156982, 2021). "Impaired leukocyte recruitment in response to TNF-α and thioglycollate-induced peritonitis in STING–/– mice compared with WT mice." (PMID 34156982, 2021). "We further investigated this mechanism using the TNF-α–induced peritonitis model in IFNAR–/– mice that are unable to initiate exogenous paracrine IFNI signaling." (PMID 34156982, 2021). "Exogenous paracrine IFNI signaling contributes to leukocyte recruitment in response to TNF-α–induced peritonitis and to T cell TEM in vitro." (PMID 34156982, 2021). "Injecting LPS into the abdominal cavity of mice can cause peritonitis and a significant increase in cytokines in mice, including IL-6, IFN-γ, IL-1β, nitric oxide (NO), and TNF-α." (PMID 34884814, 2021). "In the present study, using a murine model of LPS-induced acute peritonitis, we demonstrated administration of IL-10 inhibits inflammatory response via reduction of proinflammatory cytokines, including IL-1β, IL-18, and TNF-α in PLF and serum." (PMID 33414479, 2021). "We demonstrate that global STING–/– mice have impaired T cell recruitment in response to a TNF-α–induced model of peritonitis compared with WT mice." (PMID 34156982, 2021). "The duration and severity of the peritoneal inflammatory state is a crucial factor and epidemiologic studies in humans show a correlation between peritonitis, tumor necrosis factor alpha levels, and the severity of adhesions." (PMID 34916513, 2021). "We first used a well-established model of peritonitis induced by TNF-α to assess CD4+ T cell and Gr1+ neutrophil recruitment." (PMID 34156982, 2021).
peritonitis (continued). "For example, macrophages of C57BL/6 mice can effectively eliminate the bacterial infection in the model of cecal ligation and perforated peritonitis by producing high levels of TNF-α, IL-12 and NO, and other types I immune response molecules." (PMID 33469517, 2020). "During TNF-induced peritonitis, neutrophils rapidly transit through the high endothelial venules (HEVs) of omFALCs to enter the peritoneal cavity." (PMID 32294409, 2020). "Our work showed that ATG can significantly reduce inflammatory cell infiltration and the secretion of IL‐6 and TNF‐α in the tissues of mice with acute peritonitis, thereby alleviating inflammation and histological damage." (PMID 32960513, 2020). "As expected, CLP-induced peritonitis was associated with a strong local and systemic up-regulation of the pro-inflammatory cytokines IL-6, MCP-1, and TNFα in WT mice." (PMID 33362762, 2020). "In conclusion, ATG reduces the secretion of the proinflammatory cytokines IL‐6 and TNF‐α in acute peritonitis, thereby improving the symptoms of acute inflammation." (PMID 32960513, 2020). "Experimental E. coli peritonitis, releasing endotoxin and producing TNF-α in the liver, resulted in decreased alveolar neutrophil recruitment, phagocytosis and superoxide production in the lungs." (PMID 33108383, 2020). "Surprisingly, we found that 77His did not significantly affect Mac-1-mediated leukocyte migration and activation as assessed using thioglycollate-induced peritonitis and LPS/TNF-α-induced dermal inflammation models." (PMID 31673770, 2019). "We previously demonstrated that the hydroalcoholic extract of pomegranate leaves inhibits TNF-α production and decreases neutrophil migration in a rat model of LPS-induced acute peritonitis." (PMID 31481965, 2019). "The protective effects of IRW against LPS-induced peritonitis in a rat model were explored by examining the levels of WBCs, TNF-α, and IL-6." (PMID 30719449, 2019). "In a previous study, the hydroalcoholic extract of pomegranate leaves reduced TNF-α mRNA expression in peritoneal leukocytes obtained from rats with LPS-induced peritonitis." (PMID 31481965, 2019). "It has been well described that leukocyte recruitment and inflammation maintenance involve proinflammatory cytokines such as IL-1β, IL-6, and TNF-α in zymosan-induced peritonitis." (PMID 31236418, 2019). "It was previously demonstrated that the hydroalcoholic extract from pomegranate leaves reduces TNF-α mRNA expression in peritoneal leukocytes obtained from rats with LPS-induced peritonitis." (PMID 29675437, 2018). "(−)-α-Bisabolol (100 and 200 mg/kg) significantly inhibited myeloperoxidase (MPO) activity and decreased TNF-α levels in the peritoneal fluid of rats with induced peritonitis." (PMID 29232831, 2017). "(−)-Linalool and (−)-linalool/β-CD complex also inhibited total leukocyte migration and TNF-α levels in peritoneal fluid in the CG-induced peritonitis protocol." (PMID 29232831, 2017). "As a result, the TNF-α inhibitor, etanercept, in addition to antibiotics given in the early treatment of peritonitis results in more significant improvement of histopathological and oxidative parameters as compared to antibiotics alone." (PMID 27066189, 2016). "We also found an increase in TNF-α levels in groups with peritonitis compared with control group (TNF-α levels in group 1: 116.39 ± 42.36 pg/mL and TNF-α levels in group 2: 487.21 ± 238.44 pg/mL, p = 0.002)." (PMID 27066189, 2016). "Increased suppression of TNF-α levels with the usage of etanercept seems to be useful for limiting peritonitis." (PMID 27066189, 2016). "Omentectomized mice showed a strong reduction in peritoneal neutrophil influx at 1 h after TNFα application indicating a functional role of the greater omentum in acute peritonitis." (PMID 26940548, 2016). "The TSG6-induced decrease in TNF production resulted in diminished signs of zymosan-induced mouse peritonitis." (PMID 25562599, 2015).